CD38 (CD38 molecule)
Diseases named in the same sentence as CD38 in open-access papers (continued):
Sharing a sentence is not in itself a finding about the gene and the disease.
multiple myeloma (continued). "To investigate this hypothesis, we first characterized the relative amount of cell surface CD38 receptor in 32 Human Myeloma Cell lines (HMCLs) representative of MM molecular and mutational heterogeneity, by calculating their CD38 antibody binding capacity (ABC)." (PMID 37532787, 2023). "Moreover, such a cell line could be further genetically modified to increase the expression of myeloma-associated antigens such as CD38 or CD138." (PMID 27563813, 2016). "Multiple myeloma (MM) resistant to CD38 antibodies, two immunomodulatory drugs (IMiDs), two proteasome inhibitors (PIs), and both BCMA- and GPRC5D-directed immunotherapies defines hepta-refractory MM, a novel end-stage entity." (PMID 41703032, 2026). "Daratumumab targets CD38, an antigen which is highly expressed on the surface of multiple myeloma cells, but can also be found on erythrocytes." (PMID 41497985, 2026). "To demonstrate the usefulness of the method for immunotherapy applications, we investigated the interaction of primary multiple myeloma cells with the therapeutic monoclonal antibodies daratumumab and isatuximab and a polyclonal anti-CD38 antibody." (PMID 41637495, 2026). "Anti-CD38 antibodies such as daratumumab (DARA) and isatuximab (ISA), used in multiple myeloma (MM) therapy, bind to CD38 on red blood cells (RBCs), leading to pan-agglutination in indirect antiglobulin tests (IATs) and interfering with pretransfusion testing." (PMID 41743713, 2026). "Emerging therapies, such as daratumumab (anti-CD38 monoclonal antibody), have shown promise in AL amyloidosis when added to standard regimens (e.g., Dara-VCD), improving hematologic response and survival." (PMID 41493762, 2026). "CD38 has also emerged as a promising antigen target for MM due to its high expression in MM cells, including therapy-resistant and myeloma-initiating cells." (PMID 40092990, 2025). "To illustrate the principles of next-generation antibody engineering in multiple myeloma, we refer to a previously reported example of a T-cell–redirecting antibody targeting CD38 and CD3, designated tri-31C2." (PMID 41511330, 2025). "Daratumumab is an anti-CD38 monoclonal therapeutic antibody approved for the treatment of refractory multiple myeloma." (PMID 40145095, 2025). "CD38 is a transmembrane glycoprotein with ectoenzymatic activity that is highly and uniformly expressed on multiple myeloma cells and expressed at relatively low levels on normal lymphoid and myeloid cells." (PMID 41445795, 2025). "Daratumumab is a human immunoglobulin G1κ monoclonal antibody that binds to CD38, and it has been demonstrated to be safe and effective in patients with refractory multiple myeloma, as approved by the FDA." (PMID 41373522, 2025). "The patient’s myeloma cells expressed cd38 + cd56 + cd19-, while the plasma cells of reactive plasmacytosis showed cd38 + cd56- cd19+.Following comprehensive discussion, the diagnosis of AML combined with symptomatic MM was confirmed." (PMID 41137234, 2025). "Most transplant-ineligible patients present with multiple myeloma (MM) refractory to lenalidomide and/or anti-CD38 monoclonal antibody at first relapse and represent a difficult-to-treat population." (PMID 39757748, 2025). "Approval of proteasome inhibitors, immunomodulatory drugs, and anti-CD38 monoclonal antibodies (mAbs), such as daratumumab, has reshaped treatment patterns in patients with multiple myeloma (MM) in Japan." (PMID 39847579, 2025). "CD38 has established clinical relevance as a biomarker and therapeutic target, particularly in multiple myeloma, where anti-CD38 antibodies like daratumumab have shown significant efficacy." (PMID 40144871, 2025). "Combining maplirpacept with the anti-CD38 antibody daratumumab was also efficacious in a model of multiple myeloma." (PMID 40078999, 2025). "Similar results were also observed in CD38-positive multiple myeloma treated with [212Pb]Pb-TCMC-daratumumab." (PMID 41011187, 2025).
multiple myeloma (continued). "The remaining case was from a patient with myeloma, treated with daratumumab, an anti‐CD38 monoclonal antibody." (PMID 40769948, 2025). "Daratumumab, an anti-CD38 monoclonal antibody, is primarily used for the treatment of relapsed and refractory multiple myeloma." (PMID 39949751, 2025). "There is a lack of clear guidance on the appropriate next choice of therapy for patients with relapsed/refractory multiple myeloma who become refractory to daratumumab, an anti‐CD38 antibody." (PMID 40052837, 2025). "While two CD38-specific antibodies are approved for clinical use in relapsed/refractory multiple myeloma, it’s unclear if this approach benefits CTCL patients." (PMID 40057636, 2025). "Tremendous progress has been achieved in multiple myeloma therapy over the past 25 years with the approval of immunomodulatory drugs, proteasome inhibitors, and anti-CD38 monoclonal antibodies, resulting in a major paradigm shift." (PMID 39941892, 2025). "Daratumumab is an approved drug for multiple myeloma, which depletes CD38+ Tregs while expanding T-cells; CD38 predicts ICB response." (PMID 41583489, 2025). "Several CD38 antibodies have been developed for the treatment of multiple myeloma, where they have been an established option with an acceptable safety profile for many years." (PMID 40444214, 2025). "The remaining case was from a 48‐year‐old male patient receiving daratumumab, an anti‐CD38 antibody, for myeloma; grade 3 diarrhoea started 31 weeks after treatment initiation and required prednisone therapy." (PMID 40769948, 2025). "Despite the impressive data, the increasing use of CD38-Ab is leading to an increase in the already costly treatment of multiple myeloma, especially in the maintenance setting." (PMID 40282438, 2025). "The characterization of CD38 has been an extensive process, revealing its high expression on the plasma membranes of both normal cells and malignant myeloma cells." (PMID 40013150, 2025). "In general, myeloma cells are marked by very high CD38 expression, motivating the use of the monoclonal antibody Daratumumab (Dara), which effectively targets myeloma via several mechanisms." (PMID 40788967, 2025). "Daratumumab represents the first‐in‐class fully humanized monoclonal antibody that targets CD38 for the treatment of relapsed/refractory multiple myeloma (RRMM)." (PMID 41318167, 2025). "The rate of MRD negativity reached by combination therapies including anti-CD38 MoA daratumumab and isatuximab has been unprecedented in multiple myeloma." (PMID 40005973, 2025). "Background/Objectives: CD38-targeting monoclonal antibodies isatuximab and daratumumab have revolutionized multiple myeloma (MM) treatment, but a deeper understanding of their distinct mechanisms is crucial for therapeutic optimization." (PMID 41155915, 2025). "These early observations anticipated the subsequent clinical success of CD38-directed bispecific antibodies and underscored the potential of rational antibody engineering to amplify antitumor immunity in multiple myeloma." (PMID 41511330, 2025). "Anti-CD38 antibodies are a crucial component of these novel agents, demonstrating remarkable efficacy, particularly when combined with other standard anti-myeloma regimens, thus providing a valuable addition to the therapeutic arsenal for MM." (PMID 40563593, 2025). "For example, CD38 is found in 100% of multiple myeloma (MM) cases, 58.2% - 78.2% of acute leukemia cases, 30%−50% of chronic lymphocytic leukemia cases, and 50–80% of T-cell lymphomas." (PMID 39856752, 2025). "Background/Objectived: Daratumumab is an anti-CD38 monoclonal antibody used in the treatment of multiple myeloma." (PMID 40869587, 2025). "We thus assessed the ability of maplirpacept to combine with the anti-CD38 antibody, daratumumab, which is currently approved for use in multiple myeloma." (PMID 40078999, 2025).
multiple myeloma (continued). "CD38 antibody therapy has marked a significant advancement in managing myeloma, providing a valuable proof-of-concept for exploring in vivo questions derived from basic science." (PMID 40013150, 2025). "The most commonly used antibody was CD38; other combination therapies for myeloma, such as chemotherapy, are listed under “other”." (PMID 40282438, 2025). "Daratamumab, an United States Food and Drug Administration (FDA) approved anti-CD38 biologic for multiple myeloma, was trialled in two patients with life-threatening SLE, who clinically improved." (PMID 39863305, 2025). "Daratumumab binds with high affinity to a specific epitope on CD38 and leads to apoptosis of CD38 expressing myeloma cells by several mechanisms of action." (PMID 39311957, 2025). "Daratumumab (IgG1κ), the first monoclonal CD38 antibody approved for multiple myeloma treatment, has been explored off-label in AMR, with several case reports and series published to date." (PMID 40444214, 2025). "CD38 has high and stable expression on the surface of myeloma plasma cells in all the disease stages, which makes it an attractive target for targeted therapy." (PMID 40649828, 2025). "Since 2015, when CD38+ monoclonal antibodies were approved for the treatment of multiple myeloma patients, the therapeutic outcomes have further improved." (PMID 40027122, 2025). "Anti-CD38-based therapy has become a backbone regimen for the treatment of multiple myeloma (MM), approved in first-, second-, and third-line settings." (PMID 40144211, 2025). "CD38 is a major target for immunotherapy of myeloma, as illustrated by the clinical success of the CD38-specific monoclonal antibodies (mAbs) daratumumab and isatuximab." (PMID 41254160, 2025). "In summary, the combination of two CD38-specific BARs targeting distinct epitopes induced strong CDC against primary human myeloma cells ex vivo." (PMID 41254160, 2025). "Daratumumab, an IgG1-kappa monoclonal antibody targeting CD38, has become a pillar of multiple myeloma treatment, both in the newly diagnosed and relapsed/refractory settings." (PMID 40869587, 2025). "To determine CD38‐EVs binding to myeloma cells, we developed in vitro co‐culture systems with myeloma cells and either BMSCs (RPMI8226/BMSCs and U266/BMSCs) or HUVECs (RPMI8226/HUVECs and U266/HUVECs)." (PMID 40317915, 2025). "Monoclonal antibody therapy using CD38 as a target remains central to managing human multiple myeloma (MM)." (PMID 40013150, 2025). "Bone marrow biopsy demonstrated findings consistent with plasma cell myeloma, with CD38-positive myeloma cells comprising 80% of clonal plasma cells and κ light chain restriction." (PMID 40901511, 2025). "Recent advances in treating newly diagnosed multiple myeloma (NDMM) have explored the addition of anti-CD38 antibodies to established three-drug regimens, forming quadruplets." (PMID 40563593, 2025). "In therapy, Panobinostat induces CD38 upregulation, thereby improving the anti-myeloma effects of Daratumumab." (PMID 40013150, 2025). "CD38 is a transmembrane glycoprotein expressed on myeloma cells, as well as to a lesser extent on normal lymphoid cells, myeloid cells, and certain non-hematopoietic tissues." (PMID 41007627, 2025). "Here, we successfully engineered stable CD38‐EVs that specifically target myeloma cells while minimising uptake by non‐tumour cells." (PMID 40317915, 2025). "ATRA, a vitamin A derivative approved for in vivo use, has proven effective in enhancing CD38 levels in several ex vivo myeloma cell preparations, leading to improved efficacy of therapeutic antibodies." (PMID 40013150, 2025). "Targeting the CD38 protein on myeloma cells with monoclonal antibodies has proven to be a successful strategy." (PMID 41228289, 2025). "Daratumumab is a human IgG1κ monoclonal antibody that targets the CD38-antigen, a transmembrane glycoprotein increasingly expressed on myeloma cells." (PMID 39311957, 2025).
multiple myeloma (continued). "Daratumumab, an anti‐CD38 monoclonal antibody, since its incorporation into the treatment paradigm for newly diagnosed multiple myeloma has enhanced overall survival (OS) and progression‐free survival (PFS) in both transplant eligible and ineligible patients." (PMID 40052837, 2025). "We can understand this as a period in which the imperative to treat the cancer must be balanced against the need to allow time for the CD38 expression level in the myeloma cells to recover, so that the drug effectiveness is restored." (PMID 40788967, 2025). "Anti-CD38 monoclonal antibodies (mAbs), including daratumumab and isatuximab, have become key components of treatment for relapsed/refractory multiple myeloma (RRMM)." (PMID 40786241, 2025). "Daratumumab, a monoclonal antibody directed against CD38, is approved for the treatment of patients with multiple myeloma." (PMID 40530504, 2025). "Previously, CD38 monoclonal antibodies (including daratumumab and isatuximab) have been used to treat patients with multiple myeloma." (PMID 40649955, 2025). "Although myeloma cells appeared to take up more CD38‐EVs than EVs, the difference was insignificant." (PMID 40317915, 2025). "We further analyzed CD38 expression on EVs, an established marker of myeloma cells and other immune subsets such as NK cells and monocytes." (PMID 40948764, 2025). "Adult patients with relapsed or refractory multiple myeloma who have received at least 4 prior lines of therapy, including a proteasome inhibitor, an immunomodulatory agent, and an anti-CD38 antibody." (PMID 40626006, 2025). "A major subsequent advancement has been the development of monoclonal antibodies targeting CD38, a protein highly expressed on myeloma cells." (PMID 41154406, 2025). "Of these, daratumumab, elotuzumab, and isatuximab are indicated for multiple myeloma (MM), and daratumumab/isatuximab are anti-CD38 mAbs." (PMID 41550941, 2025). "Treatment with daratumumab or isatuximab can rapidly deplete CD38+ regulatory T cells (Tregs), myeloid-derived suppressor cells (MDSCs), and Bregs and is associated with clonal expansion of CD4+ and CD8+ T cells in myeloma patients." (PMID 41567224, 2025). "Here, we report the generation of nanobody-based BARs recognizing CD38 and assess their cytotoxicity against CD38-expressing myeloma cells in vitro and ex vivo." (PMID 41254160, 2025). "After the three main classes of drugs for MM (proteasome inhibitors [PI], immunomodulatory imide drugs [IMiD], and anti-CD38 monoclonal antibodies [CD38 mAb]) have failed patients, few effective options remain for relapsed/refractory multiple myeloma (RRMM)." (PMID 40227780, 2025). "It simultaneously targets CD3, CD28, and CD38, leading to sustained T-cell activation and specific targeting of myeloma cells." (PMID 39990653, 2025). "In the context of proteasome inhibitors (PIs) and immunomodulatory drugs as the cornerstone of treatment, the CD38 monoclonal antibodies daratumumab and isatuximab continue to play a leading role at the forefront of multiple myeloma therapy." (PMID 40005960, 2025). "Treatment of adult patients with relapsed or refractory multiple myeloma after two or more prior lines of therapy including an immunomodulatory agent, a proteasome inhibitor, and an anti-CD38 monoclonal antibody." (PMID 40129984, 2025). "For example, rituximab enhances NK cell responses against B-cell leukemias, ADCC can be triggered in neuroblastomas through anti-GD2 antibodies, and daratumumab (anti-CD38) is utilized in multiple myeloma." (PMID 40869384, 2025). "Our results demonstrate the feasibility of using CD38-specific nanobody-based BARs to effectively kill myeloma cells in vitro and ex vivo." (PMID 41254160, 2025). "Over recent years, CD38 has gained attention as a marker and therapeutic target in hematopoietic malignancies, particularly multiple myeloma." (PMID 40444214, 2025).
multiple myeloma (continued). "Currently, clinical trials of [211At]At-OKT10-B10 targeting CD38 in multiple myelomas are ongoing based on this preclinical study." (PMID 41011187, 2025). "The clinical efficacy of anti-CD38 monoclonal antibodies, such as daratumumab and isatuximab, has been demonstrated in various phases of multiple myeloma treatment, including newly diagnosed, relapsed, and refractory settings." (PMID 40144871, 2025). "Our results demonstrate the feasibility of CD38-specific nanobody-based BARs as therapeutics for multiple myeloma." (PMID 41254160, 2025). "ISB 1442 showed enhanced tumor killing in vitro compared to daratumumab on myeloma cells with varying CD38 expression levels." (PMID 40013150, 2025). "Since CD38 is typically highly overexpressed in myeloma, it can be assumed that μAu is substantially lower than μPu=1; we use 0.1 by default, although higher values are also considered." (PMID 40788967, 2025). "Orthogonal delivery was achieved by coating TiO2 with apo-transferrin (Tf) and radiolabeling daratumumab to target transferrin receptors (CD71) and CD38, respectively, which are overexpressed on rapidly proliferating myeloma cells." (PMID 41041064, 2025). "Daratumumab is a CD38 monoclonal antibody that demonstrates a substantial single-agent response rate in the treatment of multiple myeloma." (PMID 41007627, 2025). "Daratumumab is a human IgGκ monoclonal antibody targeting CD38 with a direct on-tumor and immunomodulatory mechanism of action, demonstrating greater cytotoxicity toward multiple myeloma (MM) cells ex vivo compared with analogs of other CD38 antibodies." (PMID 40301145, 2025). "Despite CD38’s still central role in MM therapy, too little attention has been paid to its broader roles–not only as a myeloma marker but also as an enzyme and adhesion molecule in physiology." (PMID 40013150, 2025). "CAR constructs that are able to recognize cells with high expression of CD38 typical for myeloma have been developed with a view to increase selectivity and decrease toxicity." (PMID 40649828, 2025). "CD38 is also being explored as a target for mAbs in combination therapy for the treatment of multiple myeloma in combination with BCMA-directed CAR NK cells with CD38 KO to avoid fratricide (NCT05182073)." (PMID 40149002, 2025). "The MAMMOTH (Monoclonal Antibodies in Multiple Myeloma: Outcomes after Therapy Failure) study investigated the natural history and outcomes of patients with disease refractory to an anti-CD38 mAb." (PMID 40422527, 2025). "The selection of CD38 as a target molecule was a key step in the design of a mAb-mediated therapy for human multiple myeloma (MM)." (PMID 40013150, 2025). "CD38 is a validated target for myeloma therapy, as evidenced by the success of CD38-specific monoclonal antibodies daratumumab and isatuximab." (PMID 41254160, 2025). "The expression of CD38 in LCE-multiple myeloma was present but slightly lower than in IGH-multiple myeloma, corresponding with the slightly less (but statistically significant) response to daratumumab ex vivo." (PMID 39699274, 2025). "CD38 plays a critical role in the pathogenesis of various lymphoid malignancies, such as mantle cell lymphoma, chronic lymphocytic leukemia, and multiple myeloma." (PMID 39996780, 2025). "The final treatment plan consisted of six cycles of mini-CHOP with daratumumab, a CD38 targeting monoclonal antibody normally used for myeloma treatment, added in after the first cycle." (PMID 39897241, 2025). "Given their potent CDC induction and versatility, nanobody-based CD38-specific BARs warrant further in vivo validation and development as therapeutics for multiple myeloma." (PMID 41254160, 2025). "Anti-CD38 mAb-based therapies have shown significant benefits in the treatment of relapsed/refractory multiple myeloma (RRMM), with robust improvements in PFS and OS across numerous studies." (PMID 40563593, 2025).